ACHE (acetylcholinesterase (Yt blood group))
Diseases named in the same sentence as ACHE in open-access papers (continued):
Sharing a sentence is not in itself a finding about the gene and the disease.
cognitive decline (71 papers, 2012 to 2025). "Ach and AChE are essential components of the system, and their dysfunction is closely linked with cognitive decline in AD." (PMID 41050397, 2025). "The current therapeutic strategies, such as the inhibition of acetylcholinesterase (AChE), aim to increase the ACh availability to prevent cognitive decline and memory loss." (PMID 40649893, 2025). "Early stages of AD are associated with neuronal loss linked to increased AChE activity, leading to the premature hydrolysis of ACh before it can facilitate cholinergic transmission, contributing to cognitive decline." (PMID 40952625, 2025). "Mn also dysregulates the cholinergic system by altering acetylcholinesterase (AChE) activity and decreasing cholinergic receptor function, both of which are implicated in cognitive decline and amyloid-β (Aβ) accumulation." (PMID 40867161, 2025). "Increased AChE activity and decreased ACh content are known to be associated with cognitive decline in AD patients." (PMID 38004471, 2023). "Altered AChE activity is associated with cognitive decline observed in the neuroinflammatory response." (PMID 37990234, 2023). "It is well known that deficits in acetylcholine are intimately related to AD-associated cognitive decline, thus forming the basis of acetylcholinesterase (AChE)-based therapy in the disease." (PMID 24860495, 2014). "Cognitive decline, anxiety, weight loss and hospitalization have been reported in this cohort to predict discontinuation of the AChE inhibitors." (PMID 24517197, 2013). "We thus propose that chronic exposure to CORT triggers dysregulation of the HPA axis, which, in turn, elicits a reduction of ChAT and AchE expression in the hippocampus and eventually causes memory and cognitive decline in the rats." (PMID 22216057, 2012). "A similar level of overlap was found with Phase 3 drugs (n = 15), with neurotransmitter receptor candidates such as Donepezil, an acetylcholinesterase (AChE) inhibitor that helps remedy loss of functioning cholinergic neurons and improves cognitive decline in AD patients." (PMID 39754192, 2025). "AChE is an important therapeutic target for treating AD because the deterioration of cholinergic neurons in the brain and the loss of cholinergic neurotransmission due to ACh degradation are among the leading causes of cognitive decline in patients with AD." (PMID 40733311, 2025). "Cognitive decline in type 2 diabetes and heavy metal exposure is closely linked to disruptions in cholinergic neurotransmission and neurotrophic support, particularly through alterations in AChE activity and BDNF levels." (PMID 40726602, 2025). "Among the cholinesterases, butyrylcholinesterase (BChE), in addition to acetylcholinesterase (AChE), can also hydrolyze acetylcholine (ACh), and a significant association between lower levels of BChE activity in the gray matter and slower rate of cognitive decline was observed." (PMID 38887858, 2024). "In addition, we found that HFD feeding led to a greater reduction in BDNF levels and elevation in AChE activity in the hippocampus of male rats compared to females, suggesting that obese males are at a greater risk for cognitive decline." (PMID 36977735, 2023). "Nonetheless, inhibitors of cholinesterases (AChE, BChE) have shown promise and compounds like donepezil, galantamine, rivastigmine and tacrine have been clinically approved for conditions associated with cognitive decline." (PMID 29056913, 2017). "Our results demonstrated that AlCl3 treatment increased AChE activity, which subsequently reduced ACh levels and impaired neurotransmission, leading to cognitive decline." (PMID 41011582, 2025). "The decrease in ACh levels is closely related to cognitive decline in AD patients, while ferulic acid can inhibit the activity of acetylcholinesterase (AChE), thereby helping to increase ACh levels in the brain." (PMID 40076984, 2025). "In AD, increased AChE activity exacerbates the cholinergic deficit, contributing to cognitive decline." (PMID 39860136, 2025).
cognitive decline (continued). "Increased AChE activity and production are pivotal components of this dysfunction, contributing to Aβ peptide deposition, enhanced neurotoxicity, and cognitive decline." (PMID 40486726, 2025). "Since cholinergic deficits contribute to cognitive decline in AD, measuring AChE activity provides insights into disease progression." (PMID 40381169, 2025). "These inhibitors prevent the hydrolysis of ACh by inhibiting AChE, thereby ensuring proper neural impulse conduction and slowing cognitive decline." (PMID 40952625, 2025). "In group VI, the levels were significantly higher than those in group V. This proved that GNL can improve cognitive decline through modulating the level of AChE." (PMID 38517361, 2024). "The reported anti-amyloidogenic features, AChE inhibitory activity and cognitive decline-preventing effects of polyphenols and flavonoids underscore their potential therapeutic relevance." (PMID 38339117, 2024). "Acetylcholinesterase (AChE) inhibitors serve as therapeutic agents that alleviate the symptoms of cognitive decline in dementia by enhancing cholinergic neurotransmitters." (PMID 38137233, 2023). "As described by Pérez-Areales and coworkers, RHE-HUP seems to inhibit AChE, a prime target in AD, since the cholinergic deficit has been widely observed in AD patients and is directly responsible for the cognitive decline." (PMID 36895036, 2023). "Alloxan-induced cognitive decline was evidenced by a significant increase in AChE activity (p < 0.001) in the hippocampus and cortex region (p < 0.01)." (PMID 36937470, 2023). "Cholinergic agents have been proposed for improving cognitive decline and the symptoms of AD and VaD, including AChE inhibitors as well as natural products such as active compounds from the herb huperzine." (PMID 36675988, 2022). "All three of the AChE inhibitors have proven to be therapeutic for AD patients such that they delay cognitive decline and stabilize or even improve cognition." (PMID 35371871, 2022). "Patients with neurodegeneration of the basal forebrain are predominantly treated with acetylcholinesterase (AchE) inhibitors to suppress the cognitive decline and to improve the memory." (PMID 35712645, 2022). "In fact, it is well documented that patients, who were placed on AChE inhibitors six months after their initial diagnosis, exhibited a more rapid cognitive decline than those who started taking the medications immediately." (PMID 35371871, 2022). "Another proposed mechanism of action for saffron’s ability to prevent cognitive decline is through a moderate (up to 30%) inhibitory activity on AChE." (PMID 34541370, 2021). "Although the development of cholinergic drugs has been highly focused on ACh inhibition and many AChE inhibitors have been developed, food constituents that are expected to counteract cognitive decline have various mechanisms besides AChE inhibition." (PMID 34637466, 2021). "The transient inhibition of AChE via a ChEI monotherapy remains the primary strategy to combat the cholinergic signaling deficit that contributes to the cognitive decline in AD." (PMID 35723391, 2021). "Galantamine is a well-known AChE inhibitor used for the treatment of cognitive decline in mild to moderate AD." (PMID 32899576, 2020). "Moreover, BChE was believed to compensate the function of AChE based on the experiment that AChE knockout mice could still survive with the normal level and localization of BChE, while silent BChE mutations in humans showed a slower rate of cognitive decline." (PMID 31311169, 2019). "Treatment of AD focuses predominantly on reducing cognitive decline with acetylcholinesterase (AChE) and butyrylcholinesterase (BChE) inhibitors." (PMID 31683761, 2019). "As AChE degrades neurotransmitters, its inhibition could help mitigate cognitive decline, supporting the neuroprotective potential of peanut shell extracts." (PMID 40548191, 2025).
cognitive decline (continued). "Impaired cholinergic neurotransmission is recognized as a major pathological mechanism that contributes to cognitive decline, with alterations in the expression of ChAT and AChE serving as key molecular indicators that reflect reduced synaptic plasticity and behavioral deficits." (PMID 41516109, 2025). "This study demonstrates that compounds derived from N. arbor-tristis can function as dual inhibitors of AChE and BChE, offering a safer and more sustainable alternative for managing AD and cognitive decline by exhibiting robust binding and favorable drug-like properties." (PMID 40700397, 2025). "Food-derived peptides containing Arg and Asn could bind to the sites of AChE to inhibit its activity, thereby increasing ACh levels to alleviate cognitive decline." (PMID 40509464, 2025). "AChE inhibition could thus increase the levels of acetylcholine and provide protective effects against cognitive decline seen in conditions like AD." (PMID 38091207, 2024). "The OEP extract demonstrated remarkable in vivo neuroprotective, antiapoptotic, and antiamnesic effects against AlCl3-induced cerebral damage and cognitive decline, which could be attributed to antioxidant and anti-AChE properties." (PMID 36557216, 2022). "Increased AChE activity was observed in the current cohort of AD rats, in agreement with previous findings, and the enzyme hydrolyzes synaptic acetylcholine, leading to cholinergic neurotransmission damage and cognitive decline." (PMID 36554305, 2022). "Consequently, in the current investigation, the STZ group exhibited prominent upregulation of β-secretase and a marked increase in AChE enzyme activity, with a subsequent increase in Aβ formation and cognitive decline, respectively." (PMID 34943114, 2021). "It has been previously reported that chrysin exhibited antioxidant activities by quenching 2,2-diphenyl-1-picrylhydrazyl (DPPH) radicals, and inhibited acetylcholinesterase (AChE) and butyrylcholinesterase (BChE), the enzymes involved in Alzheimer’s disease (AD) pathogenesis and cognitive decline." (PMID 34441689, 2021). "Furthermore, previous researches also have shown increased AChE activity in d-galactose injected group, implying deterioration of cognitive decline in cholinergic neurons." (PMID 34504131, 2021). "We provide an example of this suggesting that targeting ACHE (originally targeted to treat cognitive decline in Alzheimer’s patients) may help lower blood pressure levels." (PMID 31924771, 2020). "Thus, the inhibition of AChE shall be a potential strategy to curb the cognitive decline in AD patients." (PMID 29740000, 2018). "Clinically, cognitive decline in AD is positively correlated with reduced levels of the neurotransmitter ACh in the brain, underscoring the therapeutic rationale for acetylcholinesterase (AChE) inhibition to preserve synaptic ACh levels and mitigate symptomatology." (PMID 40806212, 2025). "From a clinical perspective, this result may guide us that more attention should be paid to cognitive decline in elderly patients in the early postoperative period, but whether short‐term changes in ChAT, AChE, and MMSE scores change clinical practice may require further in‐depth studies." (PMID 39346789, 2024). "Together, our work demonstrated that AP5 inhibited the AChE activity, decreased Aβ plaque deposition by interfering Aβ aggregation and promoting microglial Aβ phagocytosis, and suppressed inflammation, thereby rescuing neuronal and synaptic damage and relieving cognitive decline." (PMID 35860673, 2022). "The depletion or malfunction of these components has been reported in individuals experiencing cognitive decline, leading to the evaluation of whether drug candidates can affect the abundance and availability of Ch and the activity of AChE and ChAT, and elicit agonistic effects at ACh receptors." (PMID 34637466, 2021).
cognitive decline (continued). "Another review of 149 studies concluded that Ginkgo biloba, Cerebrolysin, and AChE inhibitors (donepezil, galantamine, rivastigmine, and huperzine A) may improve cognitive function and daily activities, but anti-Aβ drugs showed limited efficacy in slowing cognitive decline." (PMID 40428835, 2025). "There is a widespread notion that inhibition of AChE could prevent the metabolic processes of acetylcholine (ACh), a neurotransmitter that supports cognitive function in the cerebral cortex and hippocampus, which in turn enhances the ACh levels and delays cognitive decline." (PMID 36159481, 2022). "However, excessive AChE and lack of ChAT lead to ACh deficiency and cognitive decline." (PMID 30298092, 2018). "In addition to its enzymatic role, AChE interacts with amyloid precursor protein (APP), promoting amyloid-beta (Aβ) aggregation, which accelerates neurodegeneration and worsens cognitive decline." (PMID 40726602, 2025). "Similarly, increase in AChE at the neuromuscular junction might have contributed to a decrease in acetylcholine concentration, thereby making it fall below the threshold potential required for nerve transmission, resulting in cognitive decline and muscle fatigue." (PMID 32793135, 2020). "The preliminary biological evaluation demonstrated the beneficial effect of QTC-4-MeOBnE in preventing cognitive decline, amyloidosis, oxidative stress, up regulation of AChE and GSK3- β of STZ-induced AD mice, without showing hepatic and renal toxicity." (PMID 31086208, 2019). "Thus, the multi-dimensional effect of NAT on markers like NFκB, CREB, Tau, SP, AChE, TNF-α, and IL-6 could suggest its ability to ameliorate the neuroinflammation-induced cognitive decline in AD." (PMID 38091207, 2024). "However, the mechanism underlying cognitive decline in CKD, and the role of AChE thereto, has not been investigated so far." (PMID 30816118, 2019).
Anxiety (67 papers, 2013 to 2026). Intense feelings of nervousness, tension, or panic often arise in response to interpersonal stresses. "For example, insecticide exposure in fish has been associated with changes in anxiety-related behaviors and locomotion due to altered AChE concentrations." (PMID 41501169, 2026). "The combination of exercise and apigenin improved anxiety, memory loss, and aggression, and increased levels of antioxidant enzymes and acetylcholinesterase (AChE) activity." (PMID 38732259, 2024). "In a mouse model of psychological stress, miR-132 was elevated in the hippocampus, accompanied by and associated with reduced AChE activity, which predictably potentiates ACh signaling, and exacerbates anxiety." (PMID 28667373, 2018). "Recent research suggests that decreased anxiety-like behavior is directly associated with AChE activity of the hippocampus, since AChE knockdown in the hippocampus promotes anxiety-like behavior in mice." (PMID 26058015, 2015). "On the contrary, increasing the AchE activity in the hippocampus could reverse depression- and anxiety-like behavior in mice caused by physostigmine, an AchE inhibitor." (PMID 36973813, 2023). "A slow recovery in AChE activity coupled to a loss of GABAergic neurons may explain this hyperactivity and the development of anxiety-like behavior." (PMID 35625901, 2022). "In our study, positive correlations were also found between oxidative stress and central neural apoptosis, as well as oxidative stress and AChE level, indicating that oxidative stress, central neural apoptosis and AChE production were reciprocal causation in the anxiety process." (PMID 36687677, 2022). "As a support, serum AChE activity showed inverse, reciprocal associations with anxiety measures." (PMID 26107885, 2015). "Conversely, increased AChE activity and elevated MDA were linked to poorer memory performance and heightened anxiety." (PMID 41155598, 2025). "Hydroalcoholic extracts of Calendula have been reported to exert significant AChE inhibitory activity and robust antioxidant properties, both key mechanisms for memory protection and anxiety reduction." (PMID 41155598, 2025). "In this study, nanoparticle exposure led to uncontrolled AChE levels in zebrafish, possibly leading to the anxiety-like behavior observed." (PMID 39195719, 2024). "Mental well-being, including depression, anxiety, and stress, together with AChE, MAO, Nrf2, 8OHdG, MDA, and the density of Lactobacillus and Bifidobacterium spp., were assessed at baseline and at the end of the study." (PMID 39682956, 2024). "Peeled extract of Ananas comosus (PEAC) (pineapple) reduced IL-6 in brains of HFD rats, reduced MDA levels, and lowered anxiety behaviors and acetylcholinesterase (ACHE) activity." (PMID 39897964, 2024). "Accordingly, TAC, AChE, NE, swimming time, line crossing, anxiety index, SAP, and rearing frequency variables are grouped together and highly correlated with the first component." (PMID 37235246, 2023). "Ameliorating Sco-induced increasing of AChE activity, amnesia, anxiety, and reducing the brain antioxidant capacity." (PMID 37009463, 2023). "Degroot and Treit indicated that augmented brain ACh levels decrease anxiety, which agrees with our outcomes of reducing anxiety degree with the decreased AChE." (PMID 37235246, 2023). "Memory deficits, disturbed species typical behaviour, decreased explorative behaviour, and anxiety tendency were evident post-nephrectomy, together with increased oxidative, inflammatory changes and increased AChE activity in hippocampal homogenates." (PMID 36469209, 2023). "All doses of AO significantly improved memory, anxiety, and sleep, together with the suppression of oxidative stress, AChE, and GABA-T in the cerebral cortex and hippocampus." (PMID 36358575, 2022).